MTOR (mechanistic target of rapamycin kinase)
Diseases named in the same sentence as MTOR in open-access papers (continued):
Sharing a sentence is not in itself a finding about the gene and the disease.
cancer (continued). "First, the role of ceramide in enhancing apoptosis in some cancer cells can be mediated by the inactivation of Akt/mTOR pathway through the activation and release of protein phosphatase 1 (PP1), which then dephosphorylates AKT and causes cancer cell death." (PMID 23455468, 2013). "This signaling network is considered a validated target for innovative cancer therapy and therefore mTOR inhibitors are thought to have potent antitumor activity." (PMID 23829943, 2013). "Rheb/mTor signaling is overactivated in many types of cancers, emphasizing their roles as oncogenes." (PMID 24216995, 2013). "The mTOR signaling pathway is central to translational regulation and is a pivotal target in cancer therapeutics." (PMID 23840271, 2013). "The PI3K/Akt/mTOR pathway is one of the most frequently dysregulated signaling pathways in cancer and an important target for drug development." (PMID 23551097, 2013). "It has been reported that the mTOR inhibitors produce antitumor activities and induce autophagy, and that β-elemene also induces autophagy in certain cancer cells." (PMID 23761818, 2013). "Accumulating evidence demonstrated that mTOR was dysregulated in various cancers, its over-expression and over-activation contribute to cancer progression and drug-resistance." (PMID 23886294, 2013). "Here, we summarize current findings of the role of mTOR inhibitors and miRNAs in carcinogenesis through targeting mTOR signalling pathways and determine their potential as novel anti-cancer therapeutics." (PMID 23434669, 2013). "Through mTOR pathway, miR-204 regulated cancer cell migration and invasion, and miR-100 induced cell-cycle arrest to suppress cell proliferation and motility in bladder cancer cells." (PMID 23762265, 2013). "The multiple cell-signalling changes driving resistance and associated disease progression, nevertheless reveal potential cancer cell vulnerabilities for example mTOR, EGFR/HER2 and Src kinase." (PMID 24286369, 2013). "A majority of tumors show evidence for activation of mTOR signaling, and mTOR inhibition has been studied extensively as a potential therapy for a wide variety of cancers." (PMID 24379984, 2013). "Studies have shown that metformin can decrease the proliferation of cancer cells through 5′-AMP-activated protein kinase-(AMPK-) dependent inhibition of mTOR." (PMID 23509459, 2013). "Lee and Park demonstrated that anthocyanin activates AMPK, leading to a reduction in mTOR phosphorylation and ultimately inhibiting cancer cell growth." (PMID 23875169, 2013). "The mTOR protein is an important positive regulator of cell growth and proliferation that can influence the development of diabetes, aging, and cancer." (PMID 23954639, 2013). "The serine/threonine kinase mammalian/mechanistic target of rapamycin (mTOR) is assumed to be a critical effector for several cellular functions deregulated in cancer." (PMID 24131622, 2013). "As a result, mTOR inhibitors represent a promising therapeutic approach for cancer and solid tumors." (PMID 23886294, 2013). "A role for rapamycin-sensitive and rapamycin-insensitive mTOR signaling in cell motility and cancer metastasis is evolving but our current understanding is limited." (PMID 23476113, 2013). "we performed a case-control study by genotyping six potential functional SNPs in mTOR using genomic DNA from 1004 patients with prostate adenocarcinoma and 1051 cancer-free controls in an Eastern Chinese Han population." (PMID 23940798, 2013). "mTOR is recently demonstrated to regulate aerobic glycolysis in cancer cells and promote tumor growth through up-regulation of PKM2." (PMID 23762265, 2013). "Several studies have looked at the efficacy of combining mTOR inhibitors with miRNAs in cancer cell models." (PMID 23434669, 2013). "Such molecules are expected to circumvent the resistance of cancer cells to drugs that target upstream components of the PI3K-Akt-mTOR pathway while having only a partial effect on its global activities." (PMID 24204783, 2013).
cancer (continued). "Given the up-regulation of mTOR/PI3K pathway in numerous human cancers, several inhibitors of the mTOR pathway have been developed." (PMID 23717811, 2013). "Given the pivotal role of PI3K signalling in controlling cell growth, survival and proliferation, key components of this pathway, PI3K, mTOR (mammalian target of rapamycin) and Akt, have emerged as promising targets for cancer drug discovery." (PMID 23581296, 2013). "Some MTOR inhibitors (e.g. rapamycin, everolimus) are beginning to be used in the treatment of cancer." (PMID 24025726, 2013). "In summary, our finding clearly demonstrated that SSE has anti-cancer activity via suppression of the Akt/mTOR signaling pathway through AMPK activation, which resulted in the down-regulation of Bcl-2 and up-regulation of Beclin-1." (PMID 24053190, 2013). "Recent pre-clinical studies indicated that vertical blockade of the PI3K/AKT/mTOR pathway, i.e., combination of agents targeting more than one molecule in a signaling pathway, can produce synergistic anti-cancer efficacy with acceptable toxicity." (PMID 23818948, 2013). "The only randomised controlled trial reported to date that has assessed cancer development after conversion from a CNI to an mTOR inhibitor has been the 407 skin cancer study." (PMID 24565283, 2013). "Several studies have demonstrated that mTOR can serve as a promising therapeutic target in the future cancer treatment." (PMID 23940798, 2013). "The PI3K/AKT/mTOR pathway is frequently dysregulated in cancers and inhibition of mTOR has demonstrated the ability to modulate pro-survival pathways." (PMID 23520486, 2013). "Extensive studies have indicated that regulation of the mTOR pathway by miRNAs plays a major role in cancer progression, indicating a novel way to investigate the tumorigenesis and therapy of cancer." (PMID 23434669, 2013). "Recently, HIF pathway has been implicated in other disease contexts such as hypoxic inflammation and cancer through crosstalking with pathways like NFκB and mTOR." (PMID 23758895, 2013). "To this purpose, we analyzed mTOR expression and the effect of mTOR inhibition in cancer stem-like cells isolated from three human metastatic CRCs (CoCSCs)." (PMID 24185040, 2013). "Primary or acquired resistance to TKIs and mTOR inhibitors has become a major focus for cancer researchers." (PMID 24093097, 2013). "The PI3K/Akt/mTOR pathway is a central regulator in both normal cell physiology and in cancer proliferation, tumorigenesis, and metastasis." (PMID 23591839, 2013). "Due to its multiple roles in carcinogenesis and its common overactivation in cancer, mTOR has become an attractive target for cancer therapy and there are currently several inhibitors in clinical trials." (PMID 24073922, 2013). "The role of mTOR signalling in cancer development, progression and as a potential treatment target is increasingly evident." (PMID 24131622, 2013). "One of the major targets of AKT is the mammalian target of rapamycin (mTOR) which is also a key regulator of cell growth, proliferation, differentiation, survival, tumor cell motility, invasion and cancer metastasis." (PMID 23342114, 2013). "We further studied the effect of erlotinib resistance on the mTOR pathway, a key regulator of cancer cell growth, by measuring p-mTOR and its downstream substrate p-p70S6K." (PMID 24223799, 2013). "Aberrant stimulation of the mTOR pathway in many cancer cells, including PDAC, is eliciting intense interest for targeting this pathway." (PMID 23437362, 2013). "Activation of oncogenic signaling pathways involving PI3K/AkT/mTOR, c-Myc, Src, and Ras results in an enhanced glucose uptake and glycolytic activity, mimicking the Warburg phenotype in cancer cells." (PMID 23764021, 2013). "Oncogenic activation of mTOR induces several processes required for cancer cell growth, survival, and proliferation." (PMID 24216984, 2013).
cancer (continued). "These mTOR inhibitors are still in the early stage of evaluation; thus, their therapeutic potential for cancer remains uncertain." (PMID 23874880, 2013). "The IPA results revealed that several cancer-associated pathways, including EGF, FGF, mTOR, integrin, JAK/STAT, and ERK/MAPK signaling pathways, were overrepresented in the AA PCa versus CA PCa comparison." (PMID 23365759, 2013). "We also find that aromatase inhibitors, statins and mTOR inhibitors preferentially inhibit the in vitro growth of cancer cells with high protein synthesis rates per cell." (PMID 24279929, 2013). "Dysregulation of mTOR often appears in various kinds of cancers during the carcinogenesis and deterioration." (PMID 23555892, 2013). "Previously, mTOR has been established as a marker of angiogenesis and has been a validated target to mitigate several types of cancer." (PMID 23671696, 2013). "The PI3K/Akt/mTOR pathway plays a critical role in regulating cancer cell growth, survival, motility and metabolism." (PMID 24252186, 2013). "Recently, we showed that miR-99a, which is downregulated by the activation of Src-related oncogenic pathways, controls mTOR expression in various human cancers." (PMID 24244675, 2013). "We have however clearly shown that prolonged incubation of cancer cells with mTOR inhibitors can lead to sustained elevation of eIF2α phosphorylation." (PMID 24204783, 2013). "AMPK knockdown or mTOR overexpression impaired resveratrol-induced autophagy, suggesting that AMPK activation and mTOR inhibition is important for autophagy-mediated cancer cell death." (PMID 23875169, 2013). "This novel regulatory role of miR-99a suggests a missing link between Src and mTOR in cancer progression." (PMID 24244675, 2013). "Similar results were observed in human HCC cell lines, suggesting a positive regulatory network between SCD1 expression and AKT/mTOR activation in cancer cells." (PMID 24069385, 2013). "On the contrary, caloric restriction induce the disruption of the Akt/PI3K/mTOR cascade at least in part via AMPK activation and is frequently associated with a decreased cancer incidence of breast cancer in humans and in animal models." (PMID 24267900, 2013). "Hyperactivity of PTEN/Akt/mTOR pathway has been proven to be pro-tumorigenic in a variety of cancers including the tumourigenesis of PCa, in which Slug was known to be a down-stream effector of hypoxia inducible factor-1α (HIF-1α)." (PMID 24130883, 2013). "It has been suggested that one of the major mechanisms of AKT/mTOR in promoting tumorigenesis is by regulating cancer metabolism, especially lipogenesis." (PMID 24069385, 2013). "Our results suggest the possibility of combining SNS-032 with perifosine in a regimen that would optimize the antileukemic activity against cancer cells that are resistant to mTOR inhibitor-induced cell death." (PMID 23415012, 2013). "Dysregulated mTOR signaling is found in a variety of human cancers including hematologic, lung, breast, liver, pancreas, renal, skin, and gastrointestinal tract neoplasms." (PMID 23476113, 2013). "For example, the mammalian target of rapamycin (mTOR) has been proven to be a promising cancer target and several rapamycin-related compounds (rapalogs) are now in various stages of clinical development as anticancer agents." (PMID 23565201, 2013). "BEZ235 is a dual PI3K/mTOR inhibitor, which also has broad antiproliferative effects in a wide range of in vitro and in vivo cancer models." (PMID 23448424, 2013). "Despite this, to our knowledge, only one study investigated the effects of mTOR inhibitors in cancer stem-like cells so far." (PMID 24185040, 2013). "Included in this group of peptides were several downstream mediators of the PI3K/Akt/mTor pathway, a known oncogenic signaling pathway in human cancer." (PMID 24349301, 2013).
cancer (continued). "The activated PI3K/Akt/mammalian target of rapamycin (mTOR) signaling pathway provides major survival signals to normal and many cancer cells." (PMID 24244481, 2013). "Many cancers occur due to disregulation of MTOR signaling, and therefore development of MTOR inhibitors has been an active field in cancer research." (PMID 24025726, 2013). "Activated phosphoinositide-3 kinase (PI3K)-AKT-mammalian target of rapamycin (mTOR) signaling, a common feature of many cancer cells, increases the rate of HIF mRNA translation, leading to increased HIF expression and activity." (PMID 24216979, 2013). "Conversely, SCD1 has been found to be required for AKT/mTOR induced tumor cell proliferation in human cancer cells." (PMID 24069385, 2013). "Rapamycin treatment extends lifespan and delays cancer in mice, providing additional support for mTOR as a target for mimicking the effects of CR." (PMID 24280167, 2013). "NVP-BEZ235 is a dual PI3K/mTOR inhibitor toxic to many cancer cell lines and currently involved in clinical trials." (PMID 23935891, 2013). "Although the PI3K/Akt/mTOR axis is a promising target for the treatment of cancer, randomized phase III clinical trials reported suboptimal beneficial therapeutic effects in patients." (PMID 24381788, 2013). "The anti-diabetic drug metformin is a stereotypical DR mimetic that exerts its anti-cancer activity through a dual mechanism involving insulin-related (systemic) and mTOR-related (cell-autonomous) effects." (PMID 23986086, 2013). "AKT, as the upstream of mTOR, plays a critical role in the proliferation, survival and motility of cancer cells and it can directly phosphorylate mTOR." (PMID 23690956, 2013). "Levels of eIF4F are regulated by mTOR, and mTOR pathways are an established target for cancer therapeutics and central to translational regulation." (PMID 24086701, 2013). "Blockade of the PI3K/Akt/mTOR signaling axis has been shown to reduce glycolytic rate and lactate production in cancer in vitro." (PMID 23448424, 2013). "In conclusion we have demonstrated that eIF2α is a downstream effector of the mTOR pathway, and that excessive phosphorylation of eIF2α interferes with DNA repair processes and negatively affects survival of cancer cells." (PMID 24204783, 2013). "To investigate the effects of cancer cachexia on potential regulators of protein synthesis, we next examined the cardiac lysates for changes in the phosphorylation of AMPKα, Akt and mTOR." (PMID 23589074, 2013). "Activation of AMPK inhibits the mammalian target of rapamycin (mTOR), a protein known to be a driver of cellular survival and proliferation in human cancer and one that is activated by IGF-1." (PMID 24133632, 2013). "Dysregulation of this mTOR signaling network can participate in a variety of human disease processes including cancer." (PMID 23476113, 2013). "The activation of AMPK in cancer cells blocks cell proliferation by negatively regulating mammalian target of rapamycin (mTOR) control of protein synthesis." (PMID 23573093, 2013). "Aberrant RTK/PI3K/Akt/mTOR pathway has a key role in human cancer initiation, progression, invasion, metastasis and resistance to therapy." (PMID 25284964, 2013). "This can explain the findings that mTOR inhibition for cancer treatment being less effective than expected." (PMID 24400038, 2013). "Phosphorylated mTOR becomes activated, leading to increased proliferation, motility and survival of cancer cells." (PMID 23690956, 2013). "A subset of the cancer cell lines with a range of responses to TRAIL was selected from the panel for treatment with TRAIL combined with the PI3 Kinase/mTOR inhibitor PI-103 or the HSP90 inhibitor 17-AAG (tanespimycin)." (PMID 23852390, 2013). "In vitro studies suggested that metformin inhibits cancer cell growth by activating adenosine monophosphate protein kinase (Ampk), by inactivating the mammalian target of rapamycin (mTOR), and also by decreasing the activity of the mTOR effector S6K1." (PMID 23620761, 2013).
cancer (continued). "Targeting of PI3K-Akt-mTOR signaling became an attractive therapeutic strategy for cancer chemotherapy over the last few years." (PMID 23861714, 2013). "Since PI3K/AKT/mTOR axis has been classified among the most frequently activated pathway in cancer, members of the cascade represent an attractive target for cancer therapeutics." (PMID 23658859, 2013). "In summary, monotherapy with mTOR inhibitors has met with only modest effects clinically due mainly to the ability of some cancer cells to use signaling pathways upstream and parallel to mTOR to overcome this inhibition." (PMID 23548153, 2013). "Nevertheless, the role of mTOR inhibitors in cancer therapy continues to evolve, as new compounds are synthetized." (PMID 24185040, 2013). "Predicted targets of down-regulated miRNAs were found to be enriched in a larger number of KEGG pathways including mTOR- and ErbB-signalling pathway, and also several cancer related pathways." (PMID 24349037, 2013). "The PI3K-Akt pathway together with one of its downstream targets, the mechanistic target of rapamycin (mTOR; also known as the mammalian target of rapamycin) is a highly deregulated pathway in cancers." (PMID 23596569, 2013). "Several molecularly targeted therapies have been licensed since the last gap analysis including lapatinib and pertuzumab in HER2+ cancers and the mTOR inhibitor everolimus in ER+ve disease, which can overcome endocrine resistance." (PMID 24286369, 2013). "Coibamide A represents a natural product scaffold with potential for the study of mTOR-independent signaling and cell death mechanisms in apoptotic-resistant cancer cells." (PMID 23762328, 2013). "Over the last decade, the mTOR pathway has received great attention in order to understand its role in cancer cell behaviour." (PMID 23434669, 2013). "mTOR is frequently dysregulated in cancer cells, which is under research as a potential target for RCC patients." (PMID 23690956, 2013). "On the other hand, the FAK downstream regulator, Akt, also played a critical role in intracellular activation of cell growth and antiapoptosis for cancer survival via mTOR and NRF2 signaling pathway." (PMID 23573143, 2013). "mTOR pathway is found to be activated in cancer and drugs that inhibit mTOR are used for anticancer therapy." (PMID 24400038, 2013). "A ubiquitous pathway in the human body, Akt/mTOR was first described in cancer research as an antiapoptotic mechanism." (PMID 24744867, 2013). "One mTOR-inhibiting drug with great promise as an anti-cancer CRM is metformin, a biguanide drug that is commonly used to treat type 2 diabetes." (PMID 23986086, 2013). "Since the mTOR pathway is involved in anti-cancer drug resistance, sensitivity to mTOR inhibition in CR H2170 and H358 cell lines was tested." (PMID 24223799, 2013). "Dissecting out the mTOR-independent mechanism that Akt utilizes to regulate ribosomal biogenesis is crucial to understand the therapeutic response to Akt inhibitors in cancer." (PMID 24627779, 2013). "The PI3K/Akt/mTOR signaling pathway is well documented to be frequently deregulated and serves as an oncogenic pathway in several kinds of carcinomas." (PMID 24130883, 2013). "One observation made with mTOR inhibitors is that carcinomas can overcome these inhibitory effects by activating the insulin-like growth factor-I (IGF-I) signaling pathway." (PMID 23548153, 2013). "Our findings reveal that loss of miR-204 results in BDNF/TrkB overexpression and concomitant activation of the AKT/mTOR/Rac1 signaling pathway, leading to actin reorganization during cancer cell migration and invasion." (PMID 23285024, 2012). "Inhibition of mTor is a potential target in cancer therapy, and clinical trials with its inhibitor everolimus have shown promising results in CLL." (PMID 23072591, 2012).